AIRE (autoimmune regulator)
Diseases named in the same sentence as AIRE in open-access papers (continued):
Sharing a sentence is not in itself a finding about the gene and the disease.
Autoimmunity (continued). "Immune tolerance and the development of autoimmunity is largely controlled by the AIRE gene, estrogen is a key regulator of this gene, and reduced activity from elevated estrogen contributes to autoimmune susceptibility." (PMID 38082224, 2023). "In general, the targeted deletion of the AIRE+ mTEC subset, or the targeting of the optimal expansion of AIRE+ mTEC via genetically engineered animals, both lead to organ-specific autoimmunity." (PMID 35844592, 2022). "Our results evidenced a significant association of the S278R polymorphism of the AIRE gene with APECED-like conditions, including both patients affected by autoimmunity and immunodeficiency and patients with polyautoimmunity compared to healthy controls." (PMID 35683627, 2022). "These Treg cells stably existed in adult mice and played a role in maintaining self-tolerance to protect against the autoimmunity typical of AIRE knockout mice." (PMID 33923792, 2021). "A key player in T cell autoimmunity is the autoimmune regulator (AIRE) transcription factor, which induces tolerance over autoimmunity, by helping with self-antigen expression in thymic cells." (PMID 34064035, 2021). "Autoimmune regulator (AIRE) is a negative regulator of autoimmunity, which is differentially expressed in the male and female thymus and contributes to the gender difference of autoimmune diseases." (PMID 29662485, 2018). "One of the associated genes that seems to play a pivotal role in controlling autoimmunity is autoimmune regulator (AIRE)." (PMID 29074995, 2017). "Dysfunctional AIRE protein results in both primary immunodeficiency and tissue-specific autoimmunity." (PMID 31548517, 2017). "Mutations in the AIRE gene result in the development of APECED, a rare autoimmune condition, but reported worldwide, with a higher prevalence in genetically isolated populations." (PMID 27597936, 2016). "Even in the case of AIRE-deficiency, impaired tolerization of CD4+ T cells in the periphery by extra-thymic AIRE expressing cells likely contributes to the development of autoimmunity." (PMID 25182415, 2014). "Mutations in AIRE gene result in development of APECED, which represents the paradigm of a genetically determined failure of central tolerance leading to autoimmunity." (PMID 24167503, 2013). "Such an AIRE-independent mechanism would eliminate autoimmunity against nuclear antigens also in APECED patients." (PMID 23781320, 2013). "Additionally, reduced expression of autoimmune regulator (AIRE), another key transcription factor, contributes to the defective negative selection of self-reactive T cells, increasing the risk of autoimmunity in older adults." (PMID 40843723, 2025). "The transcription factor AIRE is crucial for preventing autoimmunity." (PMID 40507919, 2025). "Future studies are needed to determine whether these anti-Mi2/AIRE autoantibodies impair AIRE’s function in the thymus or other cells that express this transcriptional regulator, which is crucial for preventing autoimmunity." (PMID 40568090, 2025). "Surprisingly, and in contrast to most autoimmune diseases and models, there appears to be no requirement for innate immune signaling or the microbiome in the manifestation of autoimmunity in Aire−/− mice, emphasizing the importance of AIRE‐mediated central tolerance in preventing autoimmunity." (PMID 40558001, 2025). "Recently, heterozygous AIRE mutations exerting negative dominance have been identified in a syndrome with milder autoimmunity and incomplete penetrance." (PMID 38022498, 2023). "In previous studies, a high frequency of certain polymorphisms of the AIRE gene, including S278R, were discovered in autoimmune patients including those with non-APECED autoimmunity (vide supra)." (PMID 35683627, 2022). "Because peripheral Treg cannot compensate for AIRE deficiency, the absence of autoimmunity corroborated our finding that EED deficiency results only in a minor alteration of TRA representation." (PMID 34168132, 2021).
Autoimmunity (continued). "AIRE-deficiency also impairs B-lymphocyte tolerance, which contributes to the development of autoimmunity in some, but not all, tissues." (PMID 33584685, 2020). "Beyond APECED, we discuss the relevance and potential broader applicability of these findings to other interstitial lung diseases seen in secondary AIRE deficiency states such as thymoma and RAG deficiency or in common polygenic autoimmune disorders such as idiopathic Sjögren’s syndrome." (PMID 33584685, 2020). "Conversely, we expect the presence of tolerizing factors early in life to be particularly crucial during repertoire formation to avoid autoimmunity, as has been observed for the autoimmune regulator gene AIRE, for which expression is only essential during a perinatal time window." (PMID 33345776, 2020). "Such a peculiar expression of autoimmunity in patients with DS might be due to increased expression of AIRE gene, which could, in turn, interfere with autoimmune regulation." (PMID 31354636, 2019). "Moreover, age-associated infusion of thymic B cells with T-bet expression, IgG2a secretion, and diminished autoimmune regulator (AIRE) expression controlled the central T cell tolerance during aging and autoimmune disorders." (PMID 31795353, 2019). "Loss of AIRE function in humans leads to the rare autosomal recessive disorder autoimmune polyendocrine syndrome type I (APS-1), which is characterized by multi-organ autoimmunity and susceptibility to infectious diseases." (PMID 30837991, 2019). "This suggests that autoimmunity caused by AIRE mutations is not dependent on the presence of commensal microbiota." (PMID 30837991, 2019). "Furthermore, AIRE and FEZF2 mutations are associated with the development of autoimmunity in peripheral organs." (PMID 31008523, 2019). "AIRE is a transcriptional factor expressed in a small number of mTECs and involved in the intrathymic presentation of tissue-specific antigens, whose lack results in blockade of mTEC maturation and severe autoimmunity in numerous tissues." (PMID 29867988, 2018). "The locus responsible for APS1, the AIRE gene has been mapped on chromosome 21q22.3 and since its discovery APECED has represented a pivotal model to understand the mechanisms of immunological tolerance and its loss in the context of autoimmunity." (PMID 27420045, 2016). "The patient-to-patient variation argues that B cell autoimmunity resulting from AIRE deficiency is not simply an amplification of sporadic, low-level autoreactivities seen in healthy controls but has distinct origins." (PMID 27426947, 2016). "In the murine system some of the reported manifestations involve antigens that are independent of AIRE, suggesting that loss of TRAs is not an obligatory prerequisite of the autoimmunity." (PMID 24109480, 2013). "Molecular mechanisms regulating the expression of AIRE, which are likely critical for preventing autoimmunity, remain unclear." (PMID 23986760, 2013). "Thus, not all thymoma‐associated autoimmunity can be solely attributed to deficient autoantigen transcription in AIRE‐deficient thymic tumors." (PMID 41461613, 2026). "Additionally, although AIRE dysfunction is known to cause autoimmunity, we found no clinical reports indicating APECED-related manifestations in either pediatric or adult populations of anti-Mi2 autoantibody-positive patients." (PMID 40568090, 2025). "Comparing mRNA and protein expression of male and female thymus revealed that autoimmune regulator (Aire) levels were higher in males than in females, in mice and in humans, and in an MS mouse model, androgen administration protected against autoimmunity through Aire-dependent mechanisms." (PMID 38540229, 2024). "One such factor, Autoimmune Regulator (AIRE), a protein found in the thymus, has been studied in the context of central tolerance functioning as a nuclear transcription modulator, responsible for the expression of tissue-restricted antigens in specialized thymic cells that prevent autoimmunity." (PMID 36231130, 2022).
Autoimmunity (continued). "Instead, heterozygous recessive AIRE gene mutations may, although minimally, contribute to the occurrence of sporadic non-mendelian autoimmunity in the general population." (PMID 35683627, 2022). "This investigation further demonstrates that AIRE mutations are associated with common organ-specific autoimmunity with a variable phenotype ranging from classical APS-1 to a non-classical form that mimics common organ-specific autoimmunity." (PMID 27420045, 2016). "Both a lack of tDCs and AIRE deficiency are reported to lead to autoimmunity." (PMID 25334032, 2014). "Such expression is regulated by the autoimmune regulator (AIRE) transcription factor and avoids the development of self-antigen reactive cells, therefore preventing autoimmunity." (PMID 36225882, 2022). "Unsurprisingly, loss of expression of these PTAs, which is driven by the transcription factors autoimmune regulator (AIRE), deformed epidermal autoregulatory factor 1 (DEAF1), and FEZ family zinc finger 2 (Fezf2), leads to autoimmunity." (PMID 32784936, 2020). "Further, ICA1 and STAT6 were also closely related to AIRE and IRF5, two very well known autoimmunity genes." (PMID 26031516, 2015). "Likewise, it would be interesting to examine whether AIRE is overexpressed in some patients with thymomas that are associated with organ‐specific autoimmunity, although AIRE expression has been reported to be absent in most thymoma samples except for the B1 subtype." (PMID 35313042, 2022). "It is therefore possible that after thymus transplantation early thymopoiesis occurs in the absence of adequate AIRE-mediated negative selection, possibly contributing to failure of early deletion of autoreactive T-cells and post-transplantation autoimmunity." (PMID 33815417, 2021). "Other autoimmunity‐related TFs, such as ETS‐1 and AIRE, were also upregulated." (PMID 28026094, 2017). "Moreover, its expression can be transactivated by the AIRE (Autoimmune Regulator) gene, the main regulator of negative selection in the thymus, which suggests a possible involvement of this molecule in autoimmunity." (PMID 35281038, 2022). "Many studies, including the discovery of the transcription factors autoimmune regulator (AIRE) and fasciculation and elongation protein zeta family zinc finger (FEZF2), have shown that a defect in thymus central self‐tolerance is the earliest event promoting autoimmunity." (PMID 31008523, 2019). "The main lesson from recent evidence is that the mutations of AIRE can lead to various degrees of clinical autoimmunity, ranging from “classical” APECED to specific autoimmune conditions, which had not been previously mined for genetically determined conditions." (PMID 27597936, 2016). "Moreover, since the absence of AIRE is also likely to disrupt the development of natural Tregs, the defect in immunoregulatory mechanisms contributes to the emerging autoimmunity." (PMID 24109480, 2013). "Therefore, absence of the AIRE gene function may lead to spontaneous autoimmunity in either humans or mice." (PMID 33413189, 2021). "Interestingly, up to 95% of thymomas lack AIRE expression, thus leading to impaired positive and negative selection and the hypothesized development of autoimmunity and paraneoplastic syndromes." (PMID 32277368, 2020).
autoimmune disease (104 papers, 2005 to 2026). A disorder resulting from loss of function or tissue destruction of an organ or multiple organs, arising from humoral or cellular immune responses of the individual to their own tissue constituents. "In contrast to AIRE‐deficient mice, AIRE‐deficient rats develop a more severe phenotype and exhibit overt autoimmune disease." (PMID 41461613, 2026). "Compared to thymic carcinoma, thymomas are often linked to autoimmune diseases because of the reduced expression of autoimmune regulator (AIRE) genes, major histocompatibility complex (MHC) molecules and the altered thymic architecture." (PMID 40496871, 2025). "Sex hormones influence the expression of the AIRE gene, causing gender differences in autoimmune disorders." (PMID 37189748, 2023). "Because dysfunctional mutations of the AIRE gene cause onset of human autoimmune disease, it is most likely that TSA expression in mTECs is essential to suppress onset of autoimmune diseases." (PMID 38022666, 2023). "As whole-exome and genome sequencing are increasingly used in the diagnostic setting, we expect to see more heterozygous AIRE mutations in patients presenting with autoimmune disease and immunodeficiencies." (PMID 37235056, 2023). "In 12 of the remaining 20 patients with autoimmune disease, the Finnish major mutation of AIRE was excluded." (PMID 37216903, 2023). "Other relevant studies revealed that AIRE rs2075876 plays a crucial role in determining the risk for various autoimmune disorders, such as RA and SLE, which is consistent with our findings." (PMID 36902438, 2023). "Here, we describe several patients with APS-1 presenting with milder autoimmune disease, who harbor the splice mutation c.879+1G>A in AIRE causing loss of exon 7, which was confirmed by observations in a corresponding mouse model." (PMID 37909333, 2023). "It is shown that sex steroids can regulate autoimmune regulator (AIRE) locus expression, which in turn affects susceptibility to autoimmunity diseases." (PMID 35387179, 2022). "A study on Negroid and Caucasians with inflammatory-autoimmune disease who were undergoing glucocorticoid treatment showed that AIRE polymorphism plays an important essential role in GC-related biological processes and manifests to the response of its therapy." (PMID 35370680, 2022). "Deficiency for AIRE/Aire in both humans and mice results in the development of organ‐specific autoimmune disease." (PMID 35313042, 2022). "Several mutations in the AIRE gene correlate with development of organ-specific autoimmune diseases with a monogenic autosomal recessive inheritance pattern." (PMID 34991662, 2022). "Aire (autoimmune regulator) is a modulator of the body’s autoimmunity and its disruption of function (such as Aire deficiency or disabled) can lead to autoimmune diseases in humans and mice." (PMID 35450077, 2022). "PID patients with mutations in AIRE suffer from the autoimmune disease APECED (autoimmune polyendocrinopathy candidiasis ectodermal dystrophy)." (PMID 33923792, 2021). "The expression of tissue-specific antigens is partially regulated by the autoimmune regulator (AIRE), the mutation and dysfunction of which contribute to severe autoimmune diseases." (PMID 33717123, 2021). "Patients with AIRE (autoimmune regulator) gene mutations are also susceptible to Candida albicans infection and present themselves with autoimmune disorders." (PMID 34490039, 2021). "Correspondingly, loss-of-function mutations in the human AIRE gene result in a multi-organ autoimmune disorder known as autoimmune polyglandular syndrome type 1." (PMID 32338592, 2020). "AIRE controls tissue specific antigen expression by medullary thymic epithelial cells to control thymic T-cell selection, and AIRE deficiency is associated with autoimmune disease." (PMID 33658982, 2020).
autoimmune disease (continued). "Although majority of the studies reported no genotype-phenotype correlation in APS-1, a few observations suggested that certain AIRE mutations or polymorphisms were associated with common autoimmune diseases." (PMID 32358377, 2020). "Recently, the AIRE gene was identified as a genetic risk factor for several autoimmune diseases in genome wide association studies." (PMID 29849988, 2018). "The association between the AIRE rs878081 polymorphism and risk of other autoimmune diseases was examined before." (PMID 30403260, 2018). "AIRE gene polymorphism has been studied in various autoimmune disease, such as Graves’ disease, type 1 diabetic and alopecia areata." (PMID 29069728, 2017). "Certain single nucleotide polymorphisms (SNPs) in the AIRE gene have been suggested to play a role in autoimmune diseases like RA or MG." (PMID 26136751, 2015). "On the other hand, mTECs ectopically express self-tissue specific antigens under the control of a nuclear protein autoimmune regulator (Aire) in which mutation causes autoimmune disease." (PMID 26513242, 2015). "Expression of TSAs is, in part, regulated by nuclear protein autoimmune regulator (AIRE), and dysfunctional mutations in AIRE provoke autoimmune diseases in humans." (PMID 26441966, 2015). "AIRE gene has been cloned from human chromosome 21 as a pathogenic gene responsible for autoimmune disease APECED/APS-1 that exhibits autosomal recessive inheritance." (PMID 25326516, 2014). "Many ectopically expressed antigens are associated with organ-specific autoimmune diseases and it has been shown that AIRE-deficient mTECs present a decrease in the ectopic transcription of genes encoding peripheral antigens." (PMID 24917867, 2014). "Nevertheless, the same logic – that additional activation is required before the rare naïve auto-reactive cells that escape from human AIRE-deficient thymi/thymomas can induce autoimmune disease – must apply in humans too." (PMID 24592265, 2014). "Another approach has been to search for AIRE mutations in patients with isolated autoimmune diseases." (PMID 24109480, 2013). "It is a recessively inherited human autoimmune disease, caused by loss-of-function mutations in the Autoimmune Regulator (AIRE) gene." (PMID 24109480, 2013). "Mice that are deficient in the autoimmune regulator gene (Aire) have a failure in central tolerance that leads to autoreactive thymocytes, causing multi-organ autoimmune disease." (PMID 19365590, 2009). "Future research exploring how AIRE modulates the pathways involved in antigen processing and presentation may open novel ways for specific therapeutic interventions in autoimmune diseases linked to AIRE dysfunction." (PMID 41429646, 2025). "Interestingly, two single-nucleotide variants in AIRE were recently found to increase the risk of isolated autoimmune Addison's disease, supporting the concept that small changes in AIRE can predispose for autoimmune disease." (PMID 37235056, 2023). "This is important because AIRE deficiency causes a failure in optimal promiscuous gene expression, and therefore in the establishment of self-tolerance in T cells, leading to the onset of autoimmune diseases in humans and mice." (PMID 35141507, 2022). "AIRE rs2075876 and rs760426 were particularly selected for the study as systematic reviews and meta-analyses showed their significant association with RA: another systemic immune complex-mediated autoimmune disease showing common genetic risk factors with SLE." (PMID 34621318, 2021). "The LIP in neonatal mice leads to autoimmune diseases only if they are AIRE deficient." (PMID 33923792, 2021). "Indeed, many single-gene traits linked to autoimmune diseases (e.g., AIRE and CTLA-4) play important roles in the production or function of Treg cells." (PMID 33923792, 2021).